YTHDF2 (YTH N6-methyladenosine RNA binding protein F2)
Diseases named in the same sentence as YTHDF2 in open-access papers (continued):
Sharing a sentence is not in itself a finding about the gene and the disease.
glioma (60 papers, 2019 to 2025). A benign or malignant brain and spinal cord tumor that arises from glial cells (astrocytes, oligodendrocytes, ependymal cells). "The most frequent kind of adult malignant brain tumor is GBM, and YTHDF2 overexpression is clinically linked to a poor prognosis in glioma patients." (PMID 40919129, 2025). "CircMET is a m6A-modified, YTHDF2-associated circRNA and YTHDF2 is a validated glioma prognostic marker highly expressed in GBM18." (PMID 37491377, 2023). "A similar SNPs assessment found that the YTHDF2 rs3738067 variant significantly increased glioma risk in 171 pediatric patients." (PMID 36999016, 2023). "YTHDF2 was shown to be associated with poor prognosis in glioma patients, and is required for GBM cell proliferation, invasion, and tumorigenesis." (PMID 36118889, 2022). "Other bioinformatics assays revealed that a high level of m1A “writer” YTHDF2 is associated with the WHO grading of gliomas and is associated with poor prognosis." (PMID 36012529, 2022). "The present study was designed to determine the biological functions of YTHDF2 in glioma and to evaluate the association of YTHDF2 expression with glioma progression." (PMID 35661004, 2022). "Many studies have demonstrated that overexpression of YTHDF2 was significantly associated with higher malignant grades and a worse prognosis in glioma." (PMID 34631793, 2021). "To further explore the potential pathways that underlying the oncogenic role of YTHDF2 in gliomas, we analyzed the enriched pathways of genes that positively associated with YTHDF2 expression in all four datasets." (PMID 34246306, 2021). "YTHDF2 expression was positively associated with a higher malignant grade and molecular subtype of glioma and poorer prognosis." (PMID 34246306, 2021). "Notably, the overexpression of IGFBP3 can restore the tumorigenesis of glioma caused by YTHDF2 deletion in vivo." (PMID 38463397, 2024). "Increased YTHDF2 expression by IHC was associated with higher-grade gliomas." (PMID 36973285, 2023). "The expression of YTHDF2 in glioma is highly associated with malignancy and disease prognosis." (PMID 38072944, 2023). "High expression of YTHDF2 among patients with gliomas was also associated with poor survival." (PMID 36973285, 2023). "YTHDF2 was first reported in association with gliomas by informatics in 2020." (PMID 35625706, 2022). "ROC curve confirmed that the YTHDF2 expression level has diagnostic value for gliomas." (PMID 35661004, 2022). "Also, a report has pointed that YTHDF2 rs3738067 A>G polymorphism exhibits a significant inverse association with glioma risk." (PMID 34970571, 2021). "Together, these findings indicated that YTHDF2 plays an oncogenic role in gliomas and its expression is positively associated with increased malignant phenotype of gliomas, and may influence the cell cycle of glioma cells through regulation of RNA metabolism." (PMID 34246306, 2021). "YTHDF2 decreases the lifespan of glioma patients by promoting the m6A‐dependent degradation of LXRA and HIVEP2mRNA." (PMID 40919129, 2025). "Its expression can inhibit glioma cell proliferation and migration stimulated by YTHDF2 upregulation." (PMID 38365777, 2024). "In our study, we are the first to demonstrate in glioma cells that YTHDF2 binds to m6A -modified APC and GSK3β mRNA, promoting their degradation and thereby activating the Wnt-β-Catenin pathway." (PMID 38637831, 2024). "Specifically, the overexpression of YTHDF2 in glioma is due to the activation of EGFR/SRC/ERK pathway." (PMID 38398118, 2024). "The expression of YTHDF2 in diffuse gliomas promotes the deterioration of gliomas, and UBXN1, as a protein containing the UBX domain, inhibits the activation of NF-κβ by maintaining the expression of Iκβα." (PMID 38365777, 2024).
glioma (continued). "In glioma, YTHDF2 stabilizes its protein through the EGFR/SRC/ERK signaling axis, thereby affecting tumor proliferation and other biological behaviors through LXRα-dependent cholesterol homeostasis." (PMID 38637831, 2024). "To further clarify how PRMT6 transcriptionally activates YTHDF2 and then promotes malignant phenotypes in glioma, we conducted GSEA pathway analysis." (PMID 38637831, 2024). "This highlights a new role for ALKBH5 and YTHDF2 in glioma, presenting a promising target for glioma immunotherapy." (PMID 39135292, 2024). "Compared to healthy tissue, glioma specimens show varied expression of m5C regulators, including DNMTs, NSUNs, TETs, YTHDF2, ALYREF, and YBX1." (PMID 38474421, 2024). "Our study validates that PRMT6 transcriptionally activates YTHDF2, thereby promoting malignant phenotypes in glioma, a process that depends on PRMT6’s methyltransferase activity." (PMID 38637831, 2024). "Recent studies have indicated that ALKBH5 and YTHDF2 are important regulators of glioma cell proliferation." (PMID 38398118, 2024). "Previous literature has confirmed the upregulation of YTHDF2 in glioma and its promotion of glioma development and progression through various molecular mechanisms." (PMID 38637831, 2024). "Another YTH family member, YTHDF2, is also a potential target for glioma treatment, with studies linking YTHDF2 expression to glioma progression." (PMID 36831575, 2023). "For example, YTHDF2 promotes glioma malignancy by degrading UBXN1 mRNA, while METTL3-mediated m6A modification enhances glioma metastasis by stabilizing PCBP2." (PMID 38171932, 2023). "Defined prognostic risk signature: HNRNPC, ZC3H13, and YTHDF2.HNRNPC plays an important role in malignancy and contributes to the development of gliomas.High expression of HNRNPC correlates with a favourable prognosis." (PMID 36831575, 2023). "We found that several SNPs were associated with the increased risk of glioma, including the WTAP rs7766006, YTHDF2 rs3738067, and FTO rs9939609 polymorphisms." (PMID 36733406, 2023). "To determine the clinical relevance of YTHDF2 in gliomagenesis, we examined YTHDF2 expression across 72 human glioma specimens by immunohistochemical (IHC) staining." (PMID 36973285, 2023). "The m6A reader YTHDF2 plays a crucial role in maintaining the stemness of glioma stem cells by stabilizing RNA expression in glioma stem cells." (PMID 37403043, 2023). "Key findings in glioma patients in relation to m6A ‘readers’ include YTHDF2 overexpression, induced through the EGFR/SRC/ERK pathway to promote tumourigenesis, invasiveness, and cell proliferation independently associated with poor prognosis." (PMID 36831575, 2023). "Consistent with previous results, expression of YTHDF2 was upregulated in GSCs and recurrent gliomas." (PMID 37438359, 2023). "In this study, two glioma subgroups were identified based on the expression of m6A regulators, and a risk signature (ALKBH5, IGF2BP3, KIAA1429, and YTHDF2) was significantly associated with prognosis, the immune microenvironment and treatment efficacy." (PMID 36831575, 2023). "Mechanically, ALKBH5 deficiency impairs the YTHDF2-mediated stability of ZDHHC3 mRNA, thereby suppressing PD-L1 expression by accelerating PD-L1 degradation in glioma." (PMID 36566230, 2022). "Then, we used the GEPIA database to analyze the correlation between these transcription factors and YTHDF2 expression in glioma samples based on the TCGA and CGGA dataset and found that only YY1 was positively associated with YTHDF2 expression." (PMID 35661004, 2022).
glioma (continued). "The correlations among YTHDF2 expression, pathological characteristics, glioma progression and clinical outcome were evaluated." (PMID 35661004, 2022). "A single-cell study of 3321 cells from six patients with glioma demonstrated that YTHDF2 was overexpressed in malignant glioma cells and monocytes/macrophages in the TME (GSE102130)." (PMID 36120577, 2022). "To elucidate the abnormal up-regulated mechanisms of YTHDF2 in LGG tissues, we further examine the relationship between DNA methylation, CNV, and the expression of YTHDF2 in gliomas." (PMID 35661004, 2022). "Owing to the higher expression of YTHDF2 in glioma cell lines, we construction the YTHDF2 knockdown cells and using the qRT-PCR assay verify the knockdown efficiency." (PMID 35661004, 2022). "Similar to METTL3, the expression of YTHDF2 was significantly lower in differentiated glioma cells than in undifferentiated GSCs." (PMID 35682599, 2022). "We found that up-regulation of YTHDF2 was correlated with the unfavorable prognosis of glioma patients in different datasets." (PMID 35661004, 2022). "We found that YTHDF2 expression was up-regulated in glioma and its high expression was correlated with the tumor grade and poor prognosis in LGG." (PMID 35661004, 2022). "Collectively, these data indicate that YTHDF2 was up-regulated in glioma tissues and high expression of YTHDF2 was significantly correlated with the tumor grade of LGG." (PMID 35661004, 2022). "Our previous study indicated that YTHDF2 mRNA levels were significantly increased with increasing WHO glioma grade in both CGGA and TCGA datasets." (PMID 34246306, 2021). "Together, these findings showed that YTHDF2 can accelerate UBXN1 mRNA decay in gliomas via METTL3-mediated m6A modification." (PMID 34246306, 2021). "Meanwhile, in vivo and in vitro experiments have confirmed that upregulated YTHDF2 facilitated the malignant progression of glioma." (PMID 34631793, 2021). "Recently, another study also analyzed the correlation of m6A regulators and prognostic features and found that HNRNPC, WTAP, YTHDF1, and YTHDF2 were significantly upregulated in glioma tumors in patients with good OS." (PMID 34381710, 2021). "We also verified the protein expression of YTHDF2 in gliomas with different histological grade and IDH-mutant status." (PMID 34246306, 2021). "Transwell migration assays showed that YTHDF2 overexpression enhanced the migration of glioma cells." (PMID 34246306, 2021). "In cultured glioma tumor cell lines and normal human astrocytes, YTHDF2 protein is highly expressed in GBM cells, especially in GBM-derived stem cells (GSCs), as compared with lower-grade glioma cells (Hs683 and SW1783) and normal human astrocytes." (PMID 33420027, 2021). "In this study, we identified YTHDF2 as a prognostic factor for poor glioma patient survival and found that YTHDF2 overexpression in GBM cells is required for GBM cell growth, invasion, and tumor formation in vivo." (PMID 33420027, 2021). "Subsequently, IHC images selected from the HPA database also proved that TRMT6, TRMT61B, and YTHDF2 were upregulated in glioma tissues." (PMID 34631793, 2021). "We showed that both the mRNA and protein levels of YTHDF2 are positively correlated with increased grade of glioma malignancy and poor prognosis." (PMID 34246306, 2021). "We further demonstrated that elevated YTHDF2 expression promoted the proliferation and migration of these cells, which was also consistent with bioinformatics analysis of glioma RNA-seq data from four different cohorts." (PMID 34246306, 2021). "We found that among 507 lower-grade glioma patients and 378 GBM patients, only two patients were identified by YTHDF2 mutation (one V505I mutation and one R527W mutation)." (PMID 33420027, 2021). "Here, we investigated the expression levels of YTHDF2 mRNA and protein in gliomas and observed that YTHDF2 expression was positively correlated with increased glioma malignancy." (PMID 34246306, 2021).
glioma (continued). "Immunohistochemistry of 47 glioma cases revealed that the level of YTHDF2 protein was increased with increasing WHO grades in both IDH-wild-type and IDH-mutant gliomas." (PMID 34246306, 2021). "Studies have shown that YTHDF1 and YTHDF2 mRNA expression levels are positively correlated with malignancy of gliomas, with significant increases in higher grade gliomas, suggesting a role for these m6A readers in glioma progression." (PMID 33718165, 2021). "The overall survival of primary glioma patients with higher YTHDF2 expression was poorer than that of patients with low YTHDF2 expression in both datasets." (PMID 34246306, 2021). "To further validate the role of UBXN1 in YTHDF2 promotion of glioma progression and NF-κB activation, we overexpressed UBXN1 in cells overexpressing YTHDF2." (PMID 34246306, 2021). "The differential analysis showed that ALKBH1, TRMT6, TRMT10C, YTHDF1, and YTHDF2 were significantly overexpressed in high-grade gliomas." (PMID 34631793, 2021). "We also observed that UBXN1 mRNA levels were significantly stratified with the prognosis of glioma cases with high YTHDF2 expression (higher than the median value) in several datasets." (PMID 34246306, 2021). "In the current study, we investigate m6A YTH readers in GBM, and observe a correlation between increased expression of YTHDF2 and decreased survival of glioma patients." (PMID 33420027, 2021). "Similar to METTL3, YTHDF2 expression is also decreased in differentiated glioma cells compared with GSCs." (PMID 34246306, 2021). "YTHDF2 mRNA levels were also increased in molecular subgroups of primary gliomas with higher malignancy and in recurrent gliomas compared with primary cases." (PMID 34246306, 2021). "Mechanistically, YTHDF2 accelerates UBXN1 mRNA decay in gliomas by recognizing the m6A modification mediated by METTL3." (PMID 34246306, 2021). "Taken together, these findings demonstrated that elevated expression of YTHDF2 promotes glioma cell malignancy." (PMID 34246306, 2021). "Our findings confirmed that YTHDF2 promotes the malignant progression of gliomas and revealed important insight into the upstream regulatory mechanism of NF-κB activation via UBXN1 with a primary focus on m6A modification." (PMID 34246306, 2021). "Here, we aimed to elucidate the role and mechanism of the RNA N6,2′-O-dimethyladenosine (m6A) reader, YTH N6-methyladenosine RNA binding protein 2 (YTHDF2), in regulating the malignant progression of gliomas." (PMID 34246306, 2021). "To study the influence of YTHDF2 expression levels on glioma cells, we successfully knocked down YTHDF2 expression in LN229 and N33 cells using specific siRNAs." (PMID 34246306, 2021). "Elevated YTHDF2 expression was associated with decreased survival of all diffuse glioma and GBM patients in both the Chinese Glioma Genome Atlas (CGGA) and The Cancer Genome Atlas (TCGA) datasets." (PMID 34246306, 2021). "We then performed Transwell migration assays and found that YTHDF2 knockdown significantly attenuated the migration of glioma cells." (PMID 34246306, 2021). "Together, these data indicate that there are METTL3-mediated m6A modification sites on UBXN1 mRNA that have the potential to be recognized by YTHDF2 in glioma cells." (PMID 34246306, 2021). "YTHDF2 expression has been reported to be positively correlated with World Health Organization (WHO) grade of glioma." (PMID 33363140, 2020). "Consistent with our finding, a prior study revealed that YTHDF2 expression was elevated in glioma tissues with the increase of WHO grade." (PMID 33363140, 2020). "For the m6A methylation readers, the expression of HNRNPC, YTHDF1, and YTHDF2 was significantly increased in high-grade gliomas." (PMID 30810537, 2019). "Clinically, YTHDF2 overexpression is also correlated with poor glioma patient prognosis." (PMID 40469294, 2025). "The level of YTHDF2 and the level of LXRA in the TCGA glioma data set are negatively linked." (PMID 40919129, 2025).
glioma (continued). "In addition, another study demonstrated that YTHDF2 is overexpressed in glioma, which promotes its malignant progression both in vitro and in vivo." (PMID 40469294, 2025). "Recent studies have shown that YTHDF2 plays an important role in glioma." (PMID 38637831, 2024). "Moreover, we show that the impact of PRMT6 and YTHDF2 on glioma migration, invasion, and EMT depends on the activation of the Wnt-β-Catenin pathway." (PMID 38637831, 2024). "This action of YTHDF2 is dependent on METTL3-mediated m6A in gliomas." (PMID 38398118, 2024). "Furthermore, YTHDF2’s role extends to immune regulation, where its deficiency impairs the stability of ZDHHC3 mRNA, affecting PD-L1 expression and degradation in glioma." (PMID 38474421, 2024). "In glioma, YTHDF2 is essential for tumor cell proliferation by facilitating LXRA and HIVEP2 decay." (PMID 37438359, 2023). "YTHDF2 positively correlates with the grade and low prognosis of gliomas." (PMID 37063421, 2023). "In addition, the Cox regression algorithm has been used to analyze 11 related prognostic genes, including ALKBH5, YTHDF1, YTHDF2, and HNRNPC in the CGGA to predict risk scores in glioma patients." (PMID 38072944, 2023). "For example, it has been reported that DNA hypomethylation may be the reason for the up-regulation of YTHDF2 in LGG, which increases the expression of YTHDF2 by regulating the transcription process of YTHDF2 and leads to poor prognosis of glioma patients." (PMID 37602882, 2023). "Loss of function used to determine the biological function of YTHDF2 in glioma progression." (PMID 35661004, 2022). "Furthermore, the results demonstrated that the YTHDF2 protein level was increased in glioma tissues." (PMID 35661004, 2022). "The results show that YTHDF2 was the high expression in glioma cell lines, especially in U251cells." (PMID 35661004, 2022). "UBXN1 overexpression attenuates YTHDF2 to promote malignant progression of glioma, suggesting that YTHDF2 might be involved in the occurrence and malignant progression of GBM." (PMID 36118889, 2022). "Finally, qRT-PCR and IHC assay were used to validate YTHDF2 expression in glioma cells lines and tissues." (PMID 35661004, 2022). "To investigate the effect of YTHDF2 on the malignant phenotype of glioma via m6A modification in vivo, we injected luciferase-labeled U87 cells expressing an empty vector, a YTHDF2 overexpression vector, or a METTL3 overexpression vector into the brains of nude mice." (PMID 34246306, 2021). "Finally, a correlation between YTHDF2 protein expression and the expressions of p-EGFR (Y1173), p-Src (Y419), and p-ERK1/2 in human gliomas also suggested the importance of this EGFR/SRC/ERK/YTHDF2 cascade in tumor development." (PMID 33420027, 2021). "To explore whether there are m6A modification sites on UBXN1 mRNA that have the potential to be recognized by YTHDF2 in glioma cells, we performed MeRIP sequencing in GBM patient-derived N33 cells." (PMID 34246306, 2021). "Previous studies have identified YTHDF2 as a cancer-promoting gene in glioma." (PMID 34631793, 2021). "We then examined the protein levels of YTHDF2 in human glioma specimens." (PMID 33420027, 2021). "Elevated YTHDF2 promotes malignancy of gliomas in both in vitro and in vivo models." (PMID 34246306, 2021). "We demonstrate that YTHDF2 can promote cell proliferation and migration in several glioma models." (PMID 34246306, 2021). "Furthermore, Western blotting with freshly collected protein samples from eight IDH-wildtype gliomas showed that YTHDF2 protein levels were elevated in WHO grade IV tumors compared with WHO grade III tumors." (PMID 34246306, 2021). "YTHDF2 promoted the malignant progression of gliomas in both in vitro and in vivo models." (PMID 34246306, 2021).